STAT3 (signal transducer and activator of transcription 3)
Diseases named in the same sentence as STAT3 in open-access papers (continued):
Sharing a sentence is not in itself a finding about the gene and the disease.
tumor (continued). "The induction of this phenotype is mediated by the activation of STAT3, which allows the increased secretion of CCL5 and decreased secretion of TNFα leading to tumor growth." (PMID 35884845, 2022). "Activated myofibroblasts are a key orchestrating cell population in post RF ablation distant tumor growth, primarily through induction of the HGF/c-MET/STAT3 axis." (PMID 35857766, 2022). "Much like M2 macrophages, MDSCs produce STAT3 transcriptional targets, including IL-10, TGF-β, VEGF, arginase-1, and IDO, to generate an immunosuppressed, pro-tumor TME." (PMID 35406557, 2022). "In addition, the targets Cyclin D1 and Myc promote proliferation; in solid tumors an influence of Stat3 on VEGF expression could also further promote tumor growth and metastasis/tissue invasion through increased angiogenesis, a process of lower relevance for blood cancers." (PMID 36376859, 2022). "Studies, including ours, have demonstrated that PAFR activation enhances the in vitro proliferation and in vivo tumor growth of NSCLC cell lines via mechanisms involving the signal transducer and activator of transcription 3 (STAT3) signaling." (PMID 35743223, 2022). "In addition to STAT3, NFκB signaling pathway is also very important in inhibition of apoptosis in epithelial cells, as some studies have shown that inactivation of NFκB pathway inhibits the expression of anti-apoptotic genes and reduces tumor size in animal models of CAC." (PMID 35410210, 2022). "Deletion of IL30 dramatically downregulated BCL2, NFKB1, STAT3, IGF1 and CXCL5, whereas tumor suppressors, primarily SOCS3, were upregulated." (PMID 36224639, 2022). "Previous studies have reported that JAK2/STAT3 pathway regulated the expression of CCL20 and tumor angiogenesis." (PMID 35642002, 2022). "Our data support the tumor-suppressor function of SOCS3 and highlights the role of SOCS3/JAK2/STAT3 axis in PCa progression." (PMID 35818076, 2022). "Propofol can target various signaling pathways by regulating lncRNA expressions in tumor cells, such as the Wnt pathway, JAK2/STAT3 pathway, and Akt/mTOR pathway." (PMID 36506511, 2022). "The upregulation of miR-21, commonly in solid tumors, suppresses the expression of tumor suppresser genes like RECK, NFIB, TIMP3, TPM1, STAT3, etc.." (PMID 35885514, 2022). "STAT can induce tumor cell apoptosis by interfering with the MARK signaling pathway or down-regulating interleukin (IL-6) expression and STAT3 of interferon-alpha/beta signaling." (PMID 36311733, 2022). "Both STAT3 inhibitors, STX-0119 and WP1066, suppress GSC proliferation in vitro, but only STX-0119 inhibits tumor growth in a subcutaneous xenograft model of GSCs." (PMID 35740330, 2022). "The active STAT3 signaling pathway is a crucial transcription factor that can directly activate c-Myc, VEGF, MMP2/9, and other molecules, promoting tumor cell proliferation, invasion, metastasis, and angiogenesis." (PMID 35113040, 2022). "miR-30a increases the differentiation and immunosuppressive activity of MDSCs by targeting SOCS3 and stimulating JAK2/STAT3 signaling, thereby reducing CD8+ T cells infiltration and accelerating tumor progression." (PMID 36569895, 2022). "Previous studies have shown that STAT3 and autophagy levels are altered and abnormal in a variety of tumors, and STAT3 and autophagy may play a synergistic or antagonistic role in different stages of tumor pathological changes, thus promoting or inhibiting the occurrence and development of tumors." (PMID 36246567, 2022). "Activated STAT3 can directly bind to the promoter of MMP2 and VEGF to upregulate their expression, thus promoting tumor metastasis and angiogenesis." (PMID 36295083, 2022). "Further studies demonstrated that CQF significantly reduced IL-17A levels, which in turn inhibited NF-κB/IL-6/STAT3 signaling cascade, suppressed MMP9 expression and promoted tumor cell apoptosis." (PMID 35991881, 2022).
tumor (continued). "Solid Tumors: CuI (10 μM) treatment in NIH 3T3 cells led to a reduction in p-STAT3 and p-JAK2, which was confirmed in an array of tumor cell lines." (PMID 36355554, 2022). "These cytokines trigger the activation of JAK1/STAT1/NF-κB/Notch1, JAK/STAT3 β-catenin/STAT3 and PI3K/AKT signaling pathways, modulating tumor progression, stemness and metastasis." (PMID 36338755, 2022). "Interestingly, the effect of the tumor-activated versus control SCs on SCLC cell invasiveness was significantly higher, and this was associated with a higher level of expression of several genes, including the STAT3, SOCS3, BCL6, ELF3, IGF2, and IL32 genes, in SCLC cells." (PMID 36551618, 2022). "The following mechanistic investigation identifies the reduced expression of critical downstream STAT3 effectors, through which TSM-1 promotes cell cycle arrest and apoptosis in tumor cells." (PMID 36509291, 2022). "In contrast, Villin:Cre-Phd2fl/fl mice did not display any alterations in tumor growth, proliferation, apoptosis, or STAT3 activation, suggesting that IEC-specific Phd2 expression is dispensable for AOM/DSS-induced tumor growth, which validates work by others." (PMID 36509284, 2022). "Our work also demonstrated that STAT3 activation was significantly inhibited upon ALA treatment, both in the cell and tumor samples, as expected." (PMID 35370661, 2022). "After sulforaphane treatment, the STAT3/HIF‐1α/VEGF pathway was blocked and the angiogenesis and tumor growth were inhibited." (PMID 35356799, 2022). "Cytokines regulated by NF-κB and STAT3 can either be tumor-inducing (TNF, IL-23, IL-6) or tumor-inhibiting (IFNα, IFNγ, TRAIL)." (PMID 35327456, 2022). "Baseline PDX derived from P360 (BTY06) had overall low pTyr levels compared to the recurrent tumor (BTY29) that exhibited high phosphorylation of central regulator nodes, such as PIK3R1, STAT3, MAPK1, and MAPK3." (PMID 36077757, 2022). "The authors showed that increased IL17A in serum from colorectal cancer patients activated STAT3, leading to the downregulation of CXCR3 in CD8+ T cells and reduced tumor infiltration." (PMID 35270020, 2022). "They involve STAT3-inducing cytokines (IL-10, IL-6 and LIF), TGFB1 mainly expressed by TAMs, WNT7A mainly expressed by tumor cells, multiple S100 genes, semaphorins and their receptors (plexins and neuropilins), ephrins, chemokines and their receptors." (PMID 35682890, 2022). "While the crosstalk between STAT3 and ERK signaling is complex, we sought to identify its role in mediating tumor cell target therapy in our ESCC models after combined inhibition." (PMID 35614034, 2022). "IL-6 in the TME has been reported to play an important role in tumor progression and chemoresistance via activation of the JAK/STAT3 pathway." (PMID 35615263, 2022). "We showed higher DTH, increased lymphocyte proliferation, decreased tumor growth and reduced JAK2/STAT3 phosphorylation in mice treated with naringenin and CPT." (PMID 35606804, 2022). "In the case of TNBC, nanobodies against tumor-specific antigens such as TNF-α, EGFR, CD3, CTLA-4, STAT-3, AKT2 among others, have been generated and tested for targeting cancer cells." (PMID 36507540, 2022). "According to recent literature, the phosphorylated signal transducer and activator of transcription 3 (STAT3) and programmed cell death receptor ligand 1 (PDL1) complex can promote the expression of GSDMC in tumor cells." (PMID 35883480, 2022). "Apigenin can also halt STAT3, STAT5 gene expression and enhance the activity of STAT1, STAT2 and LMWPTP, which inhibits cell proliferation, tumor invasion and tumorigenesis." (PMID 35807549, 2022). "But in tumor models, EZH2 inhibits the expression of pro-inflammatory genes and pathways, such as SOCS3, STAT1, STAT3, etc.." (PMID 35432300, 2022). "Osteoclasts secrete IL-19 ligands to act on the IL-20RB of tumor cells, thus activating the JAK1/STAT3 signaling pathway to promote proliferation of disseminated tumor cells and colonization in bone." (PMID 36006737, 2022).
tumor (continued). "The STAT3/miR-130b-3p/MBNL1 feedback loop plays a vital role in mTORC1-mediated angiogenesis and tumor progression." (PMID 36217202, 2022). "Using the xCELLigence plates, we observed that combined therapy against the IL6R/STAT-3 axis and TIGIT increased the cytotoxicity of NK cells against tumor cells." (PMID 35465350, 2022). "Previous reports have shown that PELP1 regulate the phosphorylation of STAT3 (p-STAT3), and STAT3 regulate the expression of VEGFA to affect the angiogenesis of tumor." (PMID 35053547, 2022). "It was reported that STAT3 phosphorylation directly correlated with GBM tumor grade, and more than 65% of GBM tumor samples showed constitutive STAT3 activity." (PMID 35625738, 2022). "Here, knockdown of STAT3 altered calreticulin, ERp57, HSPs, and CD47 levels on the cell surface as well as the release of soluble mediators such as ATP, which stimulate the tumour antigen‐presentation ability of DCs and macrophages." (PMID 35665592, 2022). "Some of these had STAT3 signaling as a target: sunitinib reversed tumor MDSC accumulation through STAT3 or c-Kit signaling, and metformin downregulated the function of MDSCs through the AMPK/STAT3 pathway." (PMID 35572540, 2022). "We further demonstrated that IGFBP2 augmented IDO expression by activating STAT3 signaling in PDAC, thereby inducing Treg differentiation and promoting tumor progression." (PMID 36556226, 2022). "It has been reported in tumor diseases and endocrine diseases that the JAK2/STAT3 pathway can induce the macrophages transformed to M2 type." (PMID 35079347, 2022). "In preclinical NSCLC models, such as patient-derived tumor xenograft models and cell lines, response rates to EGFR TKI therapy were improved by the addition of JAK or STAT3 inhibitors." (PMID 36010693, 2022). "All targets of Amaryllidaceae alkaloids identified to date, i.e., ribosomes, eEF1α, and recently STAT3, must be considered in the design of compounds to combat both CRC cells and the tumor microenvironment." (PMID 36139106, 2022). "Some studies have shown that KPNA2 and STAT3 colocalize in the nucleoplasm of tumour cells, and IP results in fibroblast-like synoviocytes suggest that KPNA2 binds STAT3." (PMID 36578083, 2022). "The results show that STAT3 and nuclear YAP IHC staining increased in STAT3-overexpressing tissue compared to control tumor tissue." (PMID 35885009, 2022). "Similar to SD-36, KT-333 showed selective degradation of STAT3 over other STAT family members, apoptosis upon treatment of tumor cells, depletion of STAT3 and down-regulation of STAT3 target proteins." (PMID 35844493, 2022). "Some network pharmacological studies have shown that the anti-tumor-related targets of H. diffusa are closely related to MAPK-8, STAT3, and MMP9." (PMID 36188592, 2022). "LncRNA-HSD11B1-AS1 was highly expressed in melanoma cells and promoted tumor proliferation, migration and invasion by targeting IL-2/STAT-5 and IL-6/JAK/STAT-3 signaling pathways." (PMID 36601121, 2022). "By activating ERK and STAT3 signaling, CKAP2 essentially mediated the pro-tumor activities of DLEU1." (PMID 35853854, 2022). "Remarkably, we found that exogenous histidine treatment induced a reduction in the expression of tumor markers related to glycolysis (GLUT1 and HK2), inflammation (STAT3), angiogenesis (VEGFB and VEGFC), and stem cells (CD133)." (PMID 35267513, 2022). "The target gene of miR-29b-3p, signal transducer and activator of transcription 3 (STAT3), promotes differentiation of bone-marrow-derived inhibitory cells (MDSCs) and acts as a tumor promoter." (PMID 36188624, 2022).
tumor (continued). "The small-molecule STAT3 inhibitor TTI-101 inhibited anchorage-dependent and -independent growth of multiple human HNSCC cell lines in vitro and reduced tumor growth of radiation-resistant human HNSCC xenografts in vivo." (PMID 35887235, 2022). "APOA1 also regulates inflammation signals through the STAT3 signaling pathway and reduces matrix metalloproteinase-9 (MMP-9) levels, which is an important factor that promotes tumor proliferation and metastasis." (PMID 35421932, 2022). "In gastric cancer, constitutive STAT3 activation promotes VEGF-A expression and stimulates tumor angiogenesis." (PMID 35465322, 2022). "While myristoylation of FUS1 is highly essential for its ability to suppress in vivo tumor growth, myristoylated EZH2 was shown to efficiently bind with STAT3 and promote in vivo lung cancer." (PMID 36226054, 2022). "However, contrary to our findings, the majority of studies are focused on miR124 as a tumor suppressor, and it is generally accepted that miR124 inhibits cell proliferation and metastasis of cancer through suppression of several oncogenes such as STAT3, ROCK1, Slug, and ZEB." (PMID 36358691, 2022). "ING5 suppresses proliferation, migration, invasion and tumor growth of various cancer cells via the suppression of EGFR/PI3K/Akt, IL-6/STAT3, Akt/NF-κB/NF-κB/MMP-9 or IL-6/CXCL12 pathway." (PMID 36425530, 2022). "Phenethyl isothiocyanate (PEITC), combined with doxorubicin, exhibited anti-tumor effects against brain cancer, downregulating HER2 and STAT3." (PMID 36428575, 2022). "JAK2–STAT3 signalling is crucial for cancer development in both tumor cells and the tumor microenvironment, and both JAK and STAT3 have emerged as important targets for cancer treatment." (PMID 36582521, 2022). "Aberrant STAT3 activation represents an important early event during the development and progression of HNSCC and CRC, promoting tumor cell proliferation, differentiation, invasion, angiogenesis, metastasis, and the evasion of detection by the immune system." (PMID 36509291, 2022). "Formonetin inhibits cell proliferation, tube formation, and cell migration and interferes with MYC and STAT3 proteins via the RAS/ERK and JAK1/STAT3 pathways to suppress PD-L1 protein expression thereby promoting tumor cell apoptosis." (PMID 36452480, 2022). "In this study, the authors deleted the STAT3 negative regulator SOCS3, which resulted in unchecked STAT3 signaling in macrophages but overall anti-tumor effects." (PMID 35406557, 2022). "Both STAT3 signaling and autophagy have been investigated in glioma biology, but the role of autophagy in GBM tumor initiation and progression is still controversial, given its dual regulatory function in both cell death and survival." (PMID 40396025, 2022). "SC-43 showed tumor growth inhibition and apoptosis inducing by suppressing the SHP-1-dependent STAT3 expression." (PMID 35414025, 2022). "The signaling pathways of transcription 3 (STAT3) and focal adhesion kinase (FAK) affected by cratoxylumxanthone C, which were closely coupled with tumor proliferation and migration, were investigated." (PMID 36016565, 2022). "IL6/JAK/STAT3 signalling was enhanced in M1-like MΦ of the CCI patient group, which was also activated in the mouse model in the resident-like MΦs, in TC1 tumours treated with the caerin peptide gel." (PMID 36497272, 2022). "In previous studies, the IL-6/JAK/STAT3 pathway in CRC promotes tumor genesis and tumor growth, as well as inhibits tumor cell apoptosis." (PMID 36551288, 2022). "Mechanistically, ligustilide impaired the secretion of the signals from tumor cells via inhibiting the YAP nuclear transcription and expression to inactive the IL-6/STAT3 signaling." (PMID 36615387, 2022). "NDRG2 inhibits cell signaling, such as AKT-, NF-κB-, STAT3-, and TGF-β-mediated signaling, to induce tumor metastasis, and induces activation of GSK-3β which has anti-tumor effects." (PMID 36012631, 2022).
tumor (continued). "After blocking IL-6/JAK2/STAT3 pathway and inhibiting DNMT1, the proliferation of lung CSCs, the formation of spheres and the ability to initiate tumor growth decrease." (PMID 36591515, 2022). "Whole-cell lysates that block STAT3 stimulate the activation of T cells and NK cells and enhance the infiltration of toxic CD8 T cells in HCC tumor tissue, also reducing TGF-β production." (PMID 36686771, 2022). "The Western blot analysis of tumor tissues showed that the β-Ele combined with cisplatin markedly suppressed the expression of p-JAK2 and p-STAT3." (PMID 35909161, 2022). "Among these tumor markers, increased CD133 expression is mediated by the activation of STAT3 signaling, which promotes HCC progression and induces a poor response to sorafenib." (PMID 35267513, 2022). "IL-10 stimulates TAMs to activate STAT3 signaling, which promotes the release of VEGF-A and supports tumor angiogenesis." (PMID 36510315, 2022). "CD163+ TAMs produced tumor-supporting cytokines (IL-6 and CXCL2) activated STAT3 in tumor cells and supported tumor progression." (PMID 36686729, 2022). "The activity of JAK and STAT3 is enhanced due to the overexpression of pro-inflammatory cytokines like IL-6, IL-10, IL-11, and TGF-α to regulate the tumor micro-environment, which eventually create the oncogenic conditions to inhibit apoptosis." (PMID 35401182, 2022). "In summary, our present study demonstrated that overexpression of HMGA2 in CRC cells facilitated macrophage recruitment and M2 polarization via upregulating STAT3-mediated CCL2 secretion, thus promoting tumor immunosuppression in CRC." (PMID 34976223, 2022). "We conducted spheroid formation assays, which demonstrated the therapeutic effect of co-targeting STAT3 and AKT to inhibit HIF-1α signaling and decrease tumor growth in combination with cisplatin treatment." (PMID 35236823, 2022). "further revealed that silencing STAT3 in T cells allows CXCR3 (the receptor for CXCL10) to be expressed in CD8+ T cells, leading to CD8+ T cells effectively accumulating at tumor sites." (PMID 35530361, 2022). "A study found that curcumin combined with (−)-epigallocatechin-3-gallate (EGCG) reduced tumor growth and angiogenesis by inhibiting the JAK/STAT3/IL-8 signaling pathway in CRC." (PMID 36286020, 2022). "Thus, STAT3 is speculated to be one of the main targets of celastrol for suppressing tumours." (PMID 34894961, 2022). "STAT3 is overexpressed and persistently activated in TNBC and plays a key role in tumour cell proliferation, migration, invasion, metastasis, and immune evasion." (PMID 36678509, 2022). "This is especially the case for both STAT3 and STAT5 that are considered either as oncogenes or tumor suppressors, depending on the context and the delicate balance between the different counteracting transcription factors involved." (PMID 35163491, 2022). "Both Stat3 functional knockout and FAO inhibition enhance the accumulation, proliferation, and function of tumor-infiltrating Teff cells, suggesting that STAT3 diminishes CD8+ Teff cell functions via promoting FAO." (PMID 39872079, 2022). "Our results demonstrate that STAT1 and STAT3 are expressed and activated in HCC and tumor infiltrating immune cells." (PMID 35267462, 2022). "The aberrant expression and dysregulation of AMBRA1 positively and negatively control tumor formation and progression through diverse signal pathways, such as c-MYC, cyclin D, mTOR, PI3K, STAT3, and TGFβ." (PMID 36237336, 2022). "Our previous study showed that PGG inhibited the activation of STAT3 in HPV-negative HNSCC cell lines, resulting in the suppressed self-renewal activity of cancer stem cells and inhibiting the tumor spheroid formation." (PMID 35890129, 2022). "Altogether, these results indicate that STAT3 signaling induces CPT1A expression, which in turn protects Tc9 cells from ROS- or tumor-induced ferroptosis." (PMID 35192544, 2022).